WEE1 (WEE1 G2 checkpoint kinase)
Diseases named in the same sentence as WEE1 in open-access papers (continued):
Sharing a sentence is not in itself a finding about the gene and the disease.
melanoma (continued). "Significantly, the WEE1 inhibitor AZD1775 not only abrogated the suppressive H2B Y37-phosphorylation and upregulated IDH2 mRNA levels but also effectively reversed the ‘loss of 5-hmC’ phenotype in melanomas, GBMs and prostate cancer cells, as well as melanoma xenograft tumors." (PMID 29290954, 2017). "Using orthotopic preclinical models of anti-PD1 resistant, immune ‘cold’ melanoma (B16F10), the pharmacologic inhibition of AKT and WEE1 via AZD5363 (capivasertib) and MK1775 (adavosertib), respectively, was able to induce robust anti-PD1 responsiveness." (PMID 40410571, 2025). "Studies have demonstrated that CLOCK and BMAL1 affect cell proliferation by regulating the expression of Wee1, a kinase that inhibits cell cycle progression from G2 to M phase, suggesting a mechanism where disruptions in circadian rhythms could promote uncontrolled cell growth typical of melanoma." (PMID 40191195, 2025). "For instance, a study found that WEE1 was positive in 52.9% of patients with CRC, which is lower than the positive rate of WEE1 in melanoma and vulvar squamous cell carcinoma tissues." (PMID 39273409, 2024). "In a report on melanoma, the inhibition of V600EBRAF decreased WEE1 expression, suggesting that WEE1 is located downstream of V600E BRAF in the MAPK signaling cascade and that mutations in BRAF activate the MAPK pathway and increase WEE1 expression." (PMID 39335109, 2024). "A recent study identified WEE1 as a valid target to inhibit in combination with AKT3, a major target in melanoma." (PMID 35563772, 2022). "Eight inhibitors targeting Wee1, Checkpoint kinase 1/2, Aurora kinase, MEK, Polo-like kinase, PI3K and Focal adhesion kinase killed melanoma cells synergistically when combined with a BRAFi." (PMID 30728057, 2019). "The beneficial effects of combining Chk and Wee1 inhibitors have been demonstrated in BRAF mutant and wild-type melanoma cells, as well as in other human tumor cell lines." (PMID 30728057, 2019). "These indicated that the melanoma patients whose IDH2/Actin ratios are <1.8, are likely to have active/elevated WEE1/pY37-H2B signaling." (PMID 29290954, 2017). "To address this supposition, we examined the mRNA levels of WEE1, IDH2 and Actin (control) in melanoma and GBM tumors and observed that these patients exhibited elevated WEE1 mRNA expression and a significant down regulation of IDH2 transcription." (PMID 29290954, 2017). "XL888 was effective against NRAS mutant melanoma cells in vitro and in xenografts, most likely by decreasing protein levels of AKT, CDK4, and WEE1." (PMID 24743024, 2014). "In this study we demonstrated a novel cell cycle-regulating effect of the Wee1 inhibitor PD0166285, a pyrido (2,3-d) pyimidine, in B16 mouse melanoma cells." (PMID 17177986, 2006). "Interestingly, Wee1 kinase was identified as a downstream target of BRAF V600E and its expression was found to be upregulated in melanoma as compared to benign nevi." (PMID 30728057, 2019). "Next, we investigated if the combination of Wee1 and Chk inhibitors induces apoptosis rather than slowing down proliferation of parental and resistant A375 cells and of the primary M45 melanoma cells." (PMID 30728057, 2019). "Moreover, we demonstrate that tumor-relevant genes, such as FosB, WEE1, PVR, MAP1LC3B, and LGALS3, are deregulated in melanoma by direct regulation via c-Jun5." (PMID 31378787, 2019).
melanoma (continued). "Finally, we combined the most promising Chk and Wee1 inhibitors AZD7762 and MK-1775, since they showed high degrees of synergism in parental but also in several BRAF inhibitor-resistant melanoma cell lines, over longer periods of time." (PMID 30728057, 2019). "Herein, we show that WEE1 deposits the pY37-H2B marks within the tumor suppressor gene, isocitrate dehydrogenase 2 (IDH2), to repress transcription in multiple cancer cells, including glioblastoma multiforme (GBMs), melanoma and prostate cancer." (PMID 29290954, 2017). "A recent study showed that WEE1 inhibition is not able to induce immunogenic cell death or to enhance PD-L1 expression in tumor cells, but is able to synergize with radioimmunotherapy in melanoma xenografts models." (PMID 35563772, 2022). "In this paper, we will depict the current evidence on the effect of PARP, ATM, CHK1, WEE1 and ATR inhibitors both in preclinical and clinical settings in melanoma, both as monotherapy and in combination with other targets belonging to the pathways crucial for melanoma proliferation and survival." (PMID 35563772, 2022). "Specifically, we will focus on PARP, ATM, CHK1, WEE1 and ATR inhibitors, for which preclinical data as single agents, taking advantage of synthetic lethal interactions, and in combination with chemo-targeted-immunotherapy, have been growing in melanoma, encouraging the ongoing clinical trials." (PMID 35563772, 2022). "Interestingly, the five melanoma cell lines WM1963, IPC298, WM1396, WM3918, SK-MEL-2 that do not possess V600E mutation responded well to the WEE1 inhibitor, increasing IDH2 mRNA and 5-hmC levels." (PMID 29290954, 2017). "Since the status of Wee1 expression in melanomas has not been extensively studied, paraffin-embedded tissue from a panel of benign nevi and primary- and metastatic melanomas, in addition to a sample of cultured melanoncytes, were analyzed for Wee1 protein expression by immunohistochemisty." (PMID 22719872, 2012). "Furthermore, while none of the examined nevi contained >50% Wee1 immunoreactive cells, such expression was found in 4% of the primary melanomas and 22% of the metastatic tissues." (PMID 22719872, 2012). "Additionally, combination of a Wee1 and Chk inhibitor showed synergistic killing effects not only on sensitive cell lines, but also on intrinsically BRAFi- and treatment induced-resistant melanoma cells." (PMID 30728057, 2019).
ovarian carcinoma (83 papers, 2008 to 2025). A malignant neoplasm originating from the surface ovarian epithelium. "Subsequently, to quantify the survival risk for each ovarian cancer patient, we developed a risk model utilizing a multi-factorial Cox formula based on the four aforementioned genes (WEE1, PYHIN1, SEC61A2, and HAL)." (PMID 37781709, 2023). "Targeting the G2/M checkpoint mediator WEE1 has been explored as a novel treatment strategy in ovarian cancer, but mechanisms underlying its efficacy and resistance remains to be understood." (PMID 35619328, 2022). "Here, we evaluated the efficacy of the PLK1 inhibitor, volasertib, and the WEE1 inhibitor, adavosertib, along with the biomarker potential of cyclin E1 in ovarian cancer cells." (PMID 39994376, 2025). "The tyrosine kinase WEE1 is another critical kinase in ovarian cancer, and its overexpression is an independent marker of poor prognosis in HGSOC." (PMID 41354716, 2025). "Meanwhile, the EFFORT trial (NCT03579316) investigated the Wee1 inhibitor adavosertib alone and in combination with olaparib in patients with PARPi-resistant ovarian cancer, demonstrating notable efficacy in this challenging patient population." (PMID 40426953, 2025). "Taken together these experiments show combined effects of a CHK1 and WEE1 inhibitor on clonogenic survival in-vitro and growth inhibition in-vivo in ovarian cancer cell line models." (PMID 39516567, 2024). "Clinical trials of both CHK1 and WEE1 inhibitors used as single agents have shown singe agent activity in cyclin E overexpressing ovarian cancer." (PMID 39516567, 2024). "REV1 is necessary for gap suppression and tolerance of DNA damage from both intrinsic sources and ATR/WEE1-inhibition in ovarian cancer cells." (PMID 38438348, 2024). "Targeting ODF2L using an RNAi therapeutic platform sensitizes ovarian cancer cells to WEE1 inhibitor treatment in a syngeneic mouse model." (PMID 36378528, 2023). "Taken together, these data demonstrate that ODF2L expression negatively correlated with sensitivity to WEE1 inhibition in ovarian cancer." (PMID 36378528, 2023). "This study suggests that a high level of Wee1 is an independent prognostic marker for ovarian cancer." (PMID 37109350, 2023). "One approach to improve tolerability while maintaining efficacy has been to sequentially dose DDR inhibitors such as WEE1 inhibitors, which was shown to be feasible in ovarian cancer PDX models and on a recently reported Phase I trial." (PMID 37430137, 2023). "We evaluated the in vivo therapeutic potential of targeting ODF2L in combination with a WEE1 inhibitor using the ovarian cancer ID8-Luc syngeneic mouse model we previously established." (PMID 36378528, 2023). "In this review, we explore the preclinical rationale for the use of ATR inhibitors, CHK1 inhibitors, and WEE1 inhibitors, emphasizing their application to chemotherapy-resistant and PARPi-resistant ovarian cancer." (PMID 37457127, 2023). "Combined inhibition of BRD4 with ATR/WEE1 is synergistic in ARID1A mutant clear cell ovarian cancer cells." (PMID 37841875, 2023). "We also present a promising therapeutic strategy that targets ODF2L to significantly increase the sensitivity and overcome the resistance to WEE1 inhibition in ovarian cancer." (PMID 36378528, 2023). "Our findings indicated that WEE1, PYHIN1, and SEC61A2 served as risk factors impacting the prognosis of ovarian cancer, while HAL demonstrated a protective effect." (PMID 37781709, 2023). "A previous report demonstrated that the combination of a WEE1 inhibitor and a PARP inhibitor-induced replication stress and DNA damage in ovarian cancer and KRAS mutated non-small cell lung cancer." (PMID 37370065, 2023).
ovarian carcinoma (continued). "In this study, through a cell cycle machinery–related gene RNAi screen followed by multidisciplinary approaches, we identified outer dense fiber of sperm tails 2–like (ODF2L) as a central driver of resistance to WEE1 inhibition in ovarian cancer." (PMID 36378528, 2023). "To better understand the molecular biology of WEE1 inhibition in ovarian cancer, we performed RNA sequencing (RNA‐seq) analysis using OVCAR8 cells treated with AZD1775." (PMID 35619328, 2022). "Next, we characterized the functional consequences of activated PERK and IRE1α pathways in ovarian cancer cells following WEE1 inhibition." (PMID 35619328, 2022). "The remarkable synergy between coinhibition of WEE1 and IRE1α in various model systems potentiate the clinical evaluation in patients with advanced ovarian cancer." (PMID 35619328, 2022). "One of the few clinical examples demonstrated a significant increase in objective response activity in platinum-resistant ovarian cancer patients when a WEE1 inhibitor was added." (PMID 34316709, 2021). "Slipicevic and colleagues compared WEE1 IHC expression in cytology specimens from the effusions of ovarian cancer patients before and after platinum-based combination chemotherapy." (PMID 33224881, 2020). "AZD-1775, a drug that inhibits the G2–M cell-cycle checkpoint gatekeeper WEE1 kinase, has been used in multiple trials studying the treatment of lymphoma, ovarian cancer, and adult glioblastoma." (PMID 32503412, 2020). "This provides a compelling rationale for combining PARG and WEE1 inhibitors as a therapeutic strategy in ovarian cancer." (PMID 30889383, 2019). "Treatment of ovarian cancer cells with carboplatin results in increased HuR cytoplasmic expression and elevated WEE1 expression, arresting cell cycle G2/M transition." (PMID 26943573, 2016). "Combined therapy with PARP inhibitors and Wee1 inhibitors have been previously shown to induce replication stress, DNA damage, and checkpoint damage, with evidence of potential synergy in preclinical models of breast and ovarian cancer." (PMID 40678577, 2025). "In ovarian cancer cell lines, the WEE1 inhibitor AZD1775 modulates the immune response by inducing expression of endogenous retroviral elements (ERVs), which produces double-stranded RNA (dsRNA), activating IFN-mediated anti-tumor signaling and upregulating PD-L1." (PMID 40977887, 2025). "WEE1 inhibitors such as adavosertib (AZD1775) have demonstrated clinical efficacy as monotherapy or in combination with carboplatin for platinum-resistant ovarian cancer." (PMID 41354716, 2025). "Synthetic lethal SiRNA screens have identified CHK1 deletion to be synthetically lethal in leukemic cell lines exposed to WEE1 inhibitors, while SiRNA screens of ovarian cancer cells exposed to CHK1 inhibitors have identified deletion of WEE1 to be synthetically lethal." (PMID 39516567, 2024). "Indeed, synergistic activity of PARP and WEE1 inhibitors was observed in multiple ovarian cancer models." (PMID 36378528, 2023). "Our finding that ODF2L was a synthetic lethal partner with WEE1 and that loss of ODF2L sensitized the response to WEE1 inhibitors in ovarian cancer indicated that ODF2L could be a promising translational target for ovarian cancer treatment." (PMID 36378528, 2023).
ovarian carcinoma (continued). "Additionally, we investigated that silencing HJURP increased sensitivity of ovarian cancer cells to cisplatin via MYC/WEE1 axis, and HJURP participated in DNA repair of cisplatin-induced damage." (PMID 35173547, 2022). "The Wee1 inhibitor adavosertib was combined with olaparib for patients with PARPi-resistant ovarian cancer in the phase II EFFORT study, showing an overall RR of 29% in combination vs. 23% for adavosertib alone, and a median PFS of 6.8 months in combination vs. 5.5 months for adavosertib alone." (PMID 35626108, 2022). "Although Wee1 has been previously reported to be an oncogenic factor, and suppressing Wee1 exerted an anticancer effect in ovarian cancer and osteosarcoma cells, whereas in CML, on the other hand, Wee1’s engagement related with DRR has never been extensively illustrated." (PMID 36575478, 2022). "The phase II randomized, non-comparative EFFORT trial reported the efficacy of adavosertib (WEE1 inhibitor) in PARP-resistant ovarian cancer with an objective response rate (ORR) of 29% in the combination adavosertib plus olaparib arm and 23% with adavosertib alone." (PMID 35326571, 2022). "Stable depletion of SKP2, CUL1, or CDK2 rescued sensitivity to Wee1 inhibition in breast and ovarian cancer cell lines, indicating that cancer patients with overexpression of these G1/S regulatory genes could respond robustly to Wee1 inhibitors." (PMID 34671620, 2021). "Adavosertib, a WEE1 inhibitor, is currently being tested in advanced ovarian cancer." (PMID 34503204, 2021). "WEE1 expression is significantly higher following exposure to chemotherapeutic agents; the combination of chemotherapy with WEE1 inhibitors is therefore particularly promising in ovarian cancers." (PMID 32512900, 2020). "The results of our findings suggest that improved clinical outcomes for ovarian cancer patients might be better achieved using gemcitabine in combination with carboplatin and a WEE1 inhibitor as a second-line therapy." (PMID 26943573, 2016). "We also observed down-regulation of p-Wee1 (Ser642) and Myt1 in Hey and SKOv3ip cells, indicating that the efficacy of Corilagin in inducing G2/M arrest in ovarian cancer cells is possibly due to the down-regulation of cdc2 and Cyclin B1 through Wee1 and Myt1 regulation." (PMID 23410205, 2013). "Moreover, the WEE1 inhibitor adavosertib alone or in combination with olaparib was assessed in a Phase II study enrolling patients with recurrent ovarian cancer with previous progression on PARPi treatment, approximately half with a germline or somatic BRCA1/2 mutation." (PMID 37430137, 2023). "Interestingly, by analyzing The Cancer Genome Atlas (TCGA) ovarian carcinoma (OV) database, we noticed that, similar to the strong correlation between the levels of WEE1 and PKMYT1 and that of their substrate CDK1, the level of ODF2L also significantly correlated with that of CDK1." (PMID 36378528, 2023). "Furthermore, we found that silencing HJURP could modulate cisplatin sensitivity of ovarian cancer via MYC/WEE1 axis." (PMID 35173547, 2022). "In a recently presented phase II clinical trial (NCT03579316), the WEE1 inhibitor adavosertib showed promising clinical activity both as monotherapy and in combination with Olaparib, in patients with recurrent ovarian cancer irrespective of BRCA mutational status." (PMID 35052761, 2021). "In conclusion, our integrated approach identified CDK1 as a central regulatory hub in ovarian epithelial cancer and revealed Naringin as a promising dual-target inhibitor of both CDK1 and WEE1." (PMID 41009727, 2025). "Analysis of GEPIA and Oncomine databases identified a robust correlation between WEE1 and CDK1 expression in ovarian cancer, indicating potential reciprocal regulation." (PMID 41009727, 2025).